GRIK1 (glutamate ionotropic receptor kainate type subunit 1)
Description:
Ionotropic glutamate receptor that functions as a cation-permeable ligand-gated ion channel, gated by L-glutamate and the glutamatergic agonist kainic acid. L-glutamate acts as an excitatory neurotransmitter at many synapses in the central nervous system. Binding of the excitatory neurotransmitter L-glutamate induces a conformation change, leading to the opening of the cation channel, and thereby converts the chemical signal to an electrical impulse. The receptor then desensitizes rapidly and enters a transient inactive state, characterized by the presence of bound agonist. [Isoform 2]: Ionotropic glutamate receptor that functions as a cation-permeable ligand-gated ion channel, gated by L-glutamate and the glutamatergic agonist kainic acid.
Synonyms: GluK1; EAA3; GluR-5; GluR5; EEA3; GLR5
Tractability: Small molecule: an approved drug acts on it; a structure with a bound ligand is known; a high-quality ligand is known; it has a high-quality binding pocket; it belongs to a druggable protein family. Antibody: its Gene Ontology location is reachable by antibodies, with high confidence; UniProt places it where antibodies can reach, with medium confidence; UniProt predicts a signal peptide or a membrane-spanning region; the Human Protein Atlas places it where antibodies can reach. PROTAC: a small molecule that binds it is known.
Target class: Ionotropic glutamate receptor; Kainate receptor; Ligand-gated ion channel; Ion channel
Chemical probes: CHEMBL63861
Gene: Protein-coding gene on chromosome 21 (29,536,933 to 29,940,033, reverse strand). Ensembl gene ENSG00000171189.
Subcellular location: Cell membrane; Postsynaptic cell membrane
Subcellular location (Human Protein Atlas): Plasma membrane; Vesicles
Pathways (Reactome):
Neuronal System: Activation of Ca-permeable Kainate Receptor; Activation of Na-permeable kainate receptors
Gene Ontology:
Molecular function: glutamate-gated receptor activity; kainate selective glutamate receptor activity; glutamate-gated calcium ion channel activity; transmitter-gated monoatomic ion channel activity involved in regulation of postsynaptic membrane potential; ligand-gated monoatomic ion channel activity; monoatomic ion channel activity; signaling receptor activity
Biological process: central nervous system development; chemical synaptic transmission; glutamate receptor signaling pathway; modulation of chemical synaptic transmission; nervous system development; regulation of synaptic transmission, glutamatergic; synaptic transmission, glutamatergic; calcium-mediated signaling; ionotropic glutamate receptor signaling pathway; monoatomic ion transmembrane transport; monoatomic ion transport; regulation of postsynaptic membrane potential
Cellular component: kainate selective glutamate receptor complex; plasma membrane; glutamatergic synapse; postsynaptic density membrane; postsynaptic membrane; presynaptic membrane; membrane
Genetic constraint (gnomAD): Loss-of-function variants: 19 observed, 34.6 expected, observed/expected ratio (o/e) 0.55, 90% interval 0.38 to 0.81. The upper end of that interval is the gene's LOEUF score, 0.81, which puts it in group 3 of 6, group 1 being the genes least tolerant of losing a copy. Missense variants: 495 observed, 557.63 expected, observed/expected ratio (o/e) 0.89, 90% interval 0.82 to 0.96. Synonymous variants: 221 observed, 218.7 expected, observed/expected ratio (o/e) 1.01, 90% interval 0.9 to 1.13.
Homologues: Orthologues: chimpanzee GRIK1 (100% identical), macaque GRIK1 (99% identical), rabbit GRIK1 (98% identical), dog GRIK1 (97% identical), rat Grik1 (97% identical), pig GRIK1 (97% identical), mouse Grik1 (96% identical), guinea pig GRIK1 (95% identical), tropical clawed frog grik1 (84% identical), zebrafish grik1b (79% identical), zebrafish grik1a (78% identical), Drosophila melanogaster CG11155 (42% identical), and 38 more. Paralogues in human: GRIK2 (75% identical), GRIK3 (70% identical), GRIK5 (40% identical), GRIK4 (39% identical), GRIA1 (36% identical), GRIA4 (36% identical), GRIA3 (36% identical), GRIA2 (36% identical), GRID1 (28% identical), GRID2 (27% identical), GRIN1 (24% identical), GRIN2A (22% identical), and 5 more.